EXOC7 (exocyst complex component 7)
Description:
Component of the exocyst complex involved in the docking of exocytic vesicles with fusion sites on the plasma membrane. In adipocytes, plays a crucial role in targeting SLC2A4 vesicle to the plasma membrane in response to insulin, perhaps directing the vesicle to the precise site of fusion (By similarity). It is required for neuron survival and plays an essential role in cortical development (By similarity).
Synonyms: EXO70; KIAA1067; YJL085W; Exo70p; BLOM4; 2-5-3p; EX070; NEDSEBA
Tractability: Antibody: UniProt places it where antibodies can reach, with high confidence; its Gene Ontology location is reachable by antibodies, with high confidence; the Human Protein Atlas places it where antibodies can reach. PROTAC: ubiquitination databases record sites on it; its protein half-life has been measured.
Gene: Protein-coding gene on chromosome 17 (76,080,995 to 76,121,576, reverse strand). Ensembl gene ENSG00000182473.
Subcellular location: Cytoplasm, cytosol; Cell membrane; Midbody, Midbody ring
Subcellular location (Human Protein Atlas): Cytosol; Plasma membrane; Vesicles
Pathways (Reactome):
Metabolism of proteins: Insulin processing
Organelle biogenesis and maintenance: VxPx cargo-targeting to cilium
Vesicle-mediated transport: Translocation of SLC2A4 (GLUT4) to the plasma membrane
Gene Ontology:
Molecular function: protein binding; protein-macromolecule adaptor activity; phosphatidylinositol-4,5-bisphosphate binding
Biological process: positive regulation of mitotic cytokinetic process; regulation of entry of bacterium into host cell; membrane fission; mitotic cytokinesis; regulation of macroautophagy; exocytosis; protein localization to ciliary membrane
Cellular component: centriolar satellite; cleavage furrow; membrane; microtubule organizing center; midbody; cytosol; exocyst; plasma membrane; ciliary basal body; Flemming body; growth cone membrane
Genetic constraint (gnomAD): Loss-of-function variants: 51 observed, 84.71 expected, observed/expected ratio (o/e) 0.6, 90% interval 0.48 to 0.76. The upper end of that interval is the gene's LOEUF score, 0.76, which puts it in group 3 of 6, group 1 being the genes least tolerant of losing a copy. Missense variants: 742 observed, 911.81 expected, observed/expected ratio (o/e) 0.81, 90% interval 0.76 to 0.87. Synonymous variants: 327 observed, 369.18 expected, observed/expected ratio (o/e) 0.89, 90% interval 0.81 to 0.97.
Gene-disease validity (ClinGen):
ClinGen rates the evidence that EXOC7 causes each of these diseases.
complex neurodevelopmental disorder (autosomal recessive): Moderate. A disorder that involves more than one phenotype associated with the central nervous system, including but not limited to intellectual disability, autism, and seizures (epilepsy).
Homologues: Orthologues: macaque EXOC7 (100% identical), chimpanzee EXOC7 (99% identical), guinea pig EXOC7 (97% identical), rat Exoc7 (96% identical), mouse Exoc7 (96% identical), pig EXOC7 (93% identical), dog EXOC7 (88% identical), tropical clawed frog exoc7 (78% identical), zebrafish exoc7 (77% identical), Drosophila melanogaster Exo70 (32% identical), Caenorhabditis elegans exoc-7 (21% identical).
Diseases named in the same sentence as EXOC7 in open-access papers:
EXOC7 is named in the same sentence as 34 diseases in open-access papers, as found by Europe PMC text mining. Sharing a sentence is not in itself a finding about the gene and the disease. The quoted sentences say what the papers report.
breast carcinoma (10 papers, 2016 to 2023). "We found that METTL3 depletion promoted exon inclusion of the alternative exons of GNAS, MATR3, POLDIP3 and promoted skipping of the alternative exons of COMMD4, MARK3 and the non-m6A modified transcripts FASTK and EXOC7 in both breast cancer cell lines." (PMID 36725888, 2023). "Alternative splicing of EXOC7 permits isoform switching during epithelial to mesenchymal transition (EMT) in breast cancer cells, such that the mesenchymal EXOC7 isoform promotes a migratory phenotype through its ability to recruit remodelers of the actin cytoskeleton." (PMID 30086153, 2018). "Taken together, the AS events analyzed in COMMD4_AS2, EXOC7, RHOC, COMMD4_AS1 and POLDIP3 were related to a worse breast cancer prognosis, and could constitute potential prognosis biomarkers." (PMID 36725888, 2023).
invasive breast carcinoma (3 papers, 2020 to 2023). A carcinoma that infiltrates the breast parenchyma. "Additionally, COMMD4_AS1, GNAS, POLDIP3, FASTK, and RHOC AS were significantly associated with METTL3 deletion whereas AS of EXOC7 correlated with both deletion and gain of METTL3 in invasive breast carcinoma." (PMID 36725888, 2023).
microcephaly (3 papers, 2021 to 2024). A congenital or acquired developmental disorder in which the circumference of the head is smaller than normal for the person's age and sex. "Exoc7 and Exoc8, subunits of the exocyst complex, are also associated with neurodevelopmental disorders with microcephaly, seizures, and brain atrophy (NEDMISB)." (PMID 38390945, 2024). "Variants in multiple genes regulating endosomal trafficking and/or fusion of secretory vesicles [such as SMPD4, WDFY3, TRAPPC4, RAB18, VPS13B, EXOC7, EXOC8, VPS11], have been associated with the occurrence of microcephaly, cerebral atrophy, and neurodevelopmental delay." (PMID 36538041, 2023).
Spinocerebellar ataxia type 3 (2 papers, 2021 to 2023). "Interestingly, acting through Prpf19, EXOC7 counteracts the degradation of polyQ aggregation and mediates toxicity in spinocerebellar ataxia type 3 (SCA3)." (PMID 37085629, 2023).
ciliopathies (1 paper, 2025). "Mutations or deletions in genes encoding exocyst proteins, including EXOC2, EXOC4, EXOC7, and EXOC8, have been associated with ciliopathies and neural developmental disorders." (PMID 40777261, 2025).
diabetes (1 paper, 2022). "Another research also showed that different transcripts of EXOC7 influenced the efficiency of vesicle production and cytokines transport related to diabetes and inflammation." (PMID 35328051, 2022).
cancer (12 papers, 2010 to 2025). A tumor composed of atypical neoplastic, often pleomorphic cells that invade other tissues. "EXOC7 undergoes isoform switching during EMT in cancer cells, adopting functions that are beneficial to disease progression." (PMID 30086153, 2018). "These modules contained several cancer regulators such as Intraflagellar Transport (IFT) complex proteins (IFT74, IFT88), BBSome complex proteins (BBS2, BBS7, BBS9, BBS12), exocyst complex components (EXOC3, EXOC4, EXOC6B, EXOC7, and EXOC8), TTC8, TTC21B, EVC, and NEK1." (PMID 40700427, 2025). "However, TNBC, HER2-enriched and luminal B cancers additionally included exocyst-associated markers (EXOC3, EXOC4, EXOC6B, EXOC7, and EXOC8), which suggested that, unlike luminal A, these cancers not only share dysregulation of ciliogenesis but also dysfunction of transport to cilium." (PMID 40700427, 2025).
neurodevelopmental disorder (3 papers, 2023 to 2024). A behavioral and cognitive disorder with onset during the developmental period that involves impaired or aberrant development of intellectual, motor, or social functions. "Defects in the human homologues of yeast SEC5 (corresponding to human EXOC2), SEC6 (EXOC3L2), SEC8 (EXOC4), SEC15 (EXOC6B), EXO70 (EXOC7), EXO84 (EXOC8), and RHO3 (RALA) are associated with a variety of neurodegenerative and neurodevelopmental disorders." (PMID 39560727, 2024).
EXOC7 also shares sentences with these, for which no sentence is quoted: tumor (12 papers); infection (5); colon cancer (3); Brain atrophy (2); brain injury (2); cervical carcinoma (2); hepatoma (2); Alzheimer disease (1); Cerebral atrophy (1); cholangiocarcinoma (1); Cognitive impairment (1); developmental delay (1); Epithelial Ovarian Cancer (1); hepatic cancer (1); lung carcinoma (1); lymph node metastasis (1); Lymphatic Metastasis (1); melanoma (1); memory impairment (1); metastasis (1); Neurodevelopmental delay (1); pancreatic cancer (1); prostate carcinoma (1); Seizure (1); skin melanoma (1); tuberculosis (1).